ITK (IL2 inducible T cell kinase)
Diseases named in the same sentence as ITK in open-access papers (continued):
Sharing a sentence is not in itself a finding about the gene and the disease.
Sepsis (continued). "Our study showed an increased activation of ITK in CD4+ T cells as reflected by an increased % of p-ITK+ CD4+ T cells in the periphery of sepsis survivor mice." (PMID 37175808, 2023). "Sepsis-induced derangements in Nrf2 signaling were corrected by the ITK inhibitor as reflected by the restoration of Nrf2 nuclear translocation in the cerebral cortex." (PMID 37175808, 2023). "In conclusion, the present study revealed an unbalanced immune response at the transcriptome level of sepsis and identified genes for potential biomarkers of sepsis, such as ITK, CD247, MMP9, CD3D, MMP8, KLRK1, and GZMK." (PMID 35190763, 2022). "Treg cells were further elevated by the ITK inhibitor in sepsis survivor mice." (PMID 37175808, 2023). "Our data show, for the first time, that the ITK inhibition strategy may counteract sepsis-mediated depression through a reduction in IL-17A signaling in the CNS." (PMID 37175808, 2023). "Further, the ITK protein levels were also elevated in the cerebral cortex of sepsis survivor mice." (PMID 37175808, 2023). "However, how ITK signaling affects oxidative inflammation in the CNS remains unexplored with respect to sepsis." (PMID 37175808, 2023). "Sepsis-induced IL-17A signaling was greatly reduced by the ITK inhibitor." (PMID 37175808, 2023). "Our study showed elevated Foxp3/IL-10 levels and Treg cells in the CNS/periphery by the ITK inhibitor, which may counter the sepsis-mediated depression-like state in mice." (PMID 37175808, 2023). "Nadeem A proposed that ITK signaling plays a significant role in sepsis-induced acute lung injury." (PMID 36199375, 2022). "Studies have shown that ITK regulated thermal homeostasis in sepsis through affecting mast cells." (PMID 35190763, 2022). "Our study shows for the first time that early intervention using the ITK inhibitor strategy may limit sepsis-induced neuroinflammation and depression via the regulation of the Th17/Treg balance, which may improve the long-term survival and better the prognosis of septic patients." (PMID 37175808, 2023). "Therefore, we finally investigated whether ITK inhibition has the potential to modulate depression-like behavior in sepsis survivor mice." (PMID 37175808, 2023). "The ITK inhibitor mediated the downregulation of IL-17A, and subsequent oxidative stress in the CNS may protect neuronal cells from oxidative injury, which can partly mitigate sepsis-mediated behavioral problems." (PMID 37175808, 2023). "Our study shows for the first time that early intervention by ITK inhibitor strategy may limit sepsis-induced neuroinflammation and depression by regulation of Th17/Treg balance which may improve the long-term survival and better the prognosis of septic patients." (PMID 37175808, 2023). "ITK inhibition may be an effective strategy to terminate sepsis-related acute renal injury." (PMID 36199375, 2022). "Moreover, the direct administration of the ITK inhibitor to the CNS through the intracerebroventricular route should also be investigated as it will show whether targeting ITK in CNS T cells has any effect on sepsis-induced depression-like behavior." (PMID 37175808, 2023). "Our findings revealed significant decreases in CD4, CD3e, IL-7R, CD5, CD247, CD2, CD40LG, ITK, and KLRB1, and significant elevations in MMP9, LCN2, and RETN in sepsis-induced ARDS compared to controls." (PMID 37822934, 2023). "Our data showed an increased expression of p-ITK and its downstream targets in CD4+ T cells and the CNS in mice with sepsis." (PMID 37175808, 2023). "Overall, through mouse study and online patient data analysis, five genes (CD247, DOCK2, IFI35, ITK, and LCK) were reported to positively correlate with sepsis prognosis whilst only the expression of MED25 displayed a negative correlation." (PMID 37456011, 2023). "Microarray analysis has indicated abnormalities in the expression of immune-related genes in children with sepsis, including FYN, FBL, ATM, WDR75, FOXO1, and ITK." (PMID 36855207, 2023).
Sepsis (continued). "Additionally, five hub immune-related genes (CD3E, HLA-DRA, IL2RB, ITK and LAT) were identified from the protein–protein interaction network, and sepsis patients with higher expression of hub genes had a better prognosis." (PMID 38166628, 2024). "CD247, DOCK2, IFI35, ITK, LCK, and MED25 might be important targets affecting the prognosis of sepsis." (PMID 33015708, 2020). "In addition, ITK and BTK regulate the thermal homeostasis in sepsis in mice through mast cell function." (PMID 33015708, 2020). "Sepsis development/progression in mice could be regulated by changing the LPS amount, as an example of using different doses of LPS to set survival and death groups in the discovery of six genes (CD247, DOCK2, IFI35, ITK, LCK and MED25)." (PMID 37456011, 2023). "However, the role of ITK in T-cell functions in patients with sepsis has not been fully evaluated." (PMID 33132754, 2020).
T-cell lymphoma (13 papers, 2013 to 2023). "Years before the first patient with ITK deficiency was diagnosed, ITK-SYK translocations were found in individuals with T cell lymphoma." (PMID 29867957, 2018). "Studies of ASK120067 for treatment of T-cell lymphoma via targeting ITK is also worth trying because ASK120067 is safe and well-tolerated in clinical trial against lung cancer." (PMID 36588692, 2022). "T cell receptor signaling has been reported to play a role in the progression of extranodal NK/T cell lymphoma and to activate the ITK/NF-κB/GATA-3 axis to promote chemoresistance in T cell lymphomas." (PMID 33766042, 2021). "Since the inhibition of TCR signaling had been demonstrated to overcome the resistance to chemotherapy in T cell lymphomas, the antitumor effects of the ITK inhibitor and conventional chemotherapies were further investigated in our experiment." (PMID 30814910, 2019). "Similar results were also observed in Jurkat and Hut-78 cells, which indicated that ITK expression is critical for the growth of malignant T cell lymphoma cells." (PMID 30814910, 2019). "The knockdown efficacy of the three individual ITK shRNAs in malignant T cell lymphoma cell lines was confirmed by Western blotting analysis." (PMID 30814910, 2019). "Consistent with previous studies, inhibition of ITK also suppressed the migration and invasion of malignant T-cell lymphoma through directly inhibiting RhoA and FAK." (PMID 30814910, 2019). "All these results supporting the role of the key TCR signaling regulatory tyrosine kinase ITK suggested a therapeutic target for the treatment of patients with ITK-expressing T cell lymphomas." (PMID 30814910, 2019). "Here we determine synergistic combinations with ibrutinib or ONO-7790500 a highly specific ITK inhibitor, and report potential enhancement of activity to be taken forward in further pre-clinical testing in mouse models of T-cell lymphoma." (PMID 30242208, 2018). "In T-cell lymphoma, Syk is fused to the Tec family tyrosine kinase ITK, forming a protein consisting of the PH domain of ITK fused to the kinase domain of Syk." (PMID 24116232, 2013). "Our data could also provide: i) a new reference for the development of small-molecule inhibitors of ITK; ii) deeper insights into the clinical treatment of T-cell lymphoma by targeting ITK." (PMID 36588692, 2022). "In addition, to examine the selectivity of SY-1530 in cells, we used the Pfeiffer and DOHH2 B-cell lymphoma cell lines, which endogenously express BTK, and the Jurkat T-cell lymphoma cell line, which expresses ITK." (PMID 34264564, 2021). "In this paper, western blotting exhibited that ITK inhibitor could also downregulate the activity of Notch1 level in malignant T-cell lymphoma cell lines." (PMID 30814910, 2019). "Thus, ITK inhibition induced cytotoxic effects on T-cell lymphoma cells through inducing the apoptosis or blocking cell cycle progression." (PMID 30814910, 2019). "ITK inhibitors could be treatment for T-cell lymphoma that is difficult to manage." (PMID 36588692, 2022). "However, the activation status and functional role of ITK in T-cell lymphomas is still unclear." (PMID 30814910, 2019). "Multiple chemical analogs have been reported, but selective inhibitors of ITK approved for the treatment of T-cell lymphoma are lacking." (PMID 36588692, 2022).
autoimmune disease (12 papers, 2015 to 2025). A disorder resulting from loss of function or tissue destruction of an organ or multiple organs, arising from humoral or cellular immune responses of the individual to their own tissue constituents. "Regulation of NK cell function by targeting ITK is associated not only with improved tumor immune surveillance and viral immunity, but also with reduced severity of autoimmune diseases." (PMID 40725440, 2025). "Researchers have shown that ITK is involved in the pathogenesis of autoimmune diseases and carcinogenesis, and the loss of ITK function due to mutation in patients can lead to EBV-associated lymphoproliferation." (PMID 37465420, 2023). "TFKs, such as TEC, BTK, and ITK, have been identified as therapeutic targets of autoimmune disorders and cancers." (PMID 41567642, 2025). "Currently, ITK inhibitors in clinical development are primarily targeting T cell-mediated autoimmune diseases." (PMID 41567642, 2025). "Studies have shown that ITK is involved in the pathogenesis of autoimmune diseases, including rheumatoid arthritis, systemic lupus erythematosus, multiple sclerosis, and IBD30." (PMID 37080976, 2023). "Studies have shown that ITK is a key regulator of T lymphocytes and plays a critical role in the pathogenesis of autoimmune diseases." (PMID 35190763, 2022). "Studies have shown that ITK is involved in the pathogenesis of autoimmune diseases as well as in carcinogenesis." (PMID 32808093, 2020). "A recent work revealed that CD28 and ITK signaling regulate the trafficking of self-reactive T cells to target tissues in an autoimmune disease model, and pharmacological inhibition of ITK prevented this trafficking." (PMID 30627129, 2018). "Our data suggest that targeting ITK in human T cells may be an effective approach to boost TREG in the context of autoimmune diseases, but concomitant inhibition of other Tec family kinases may negate this effect." (PMID 31022269, 2019). "This ITK/RLK dual inhibitor was approved for the treatments of T-cell or NK cell malignancies as well as inflammatory and autoimmune diseases, such as psoriasis, psoriatic arthritis, rheumatoid arthritis, multiple sclerosis, and irritable bowel disease." (PMID 41567642, 2025). "ITK has primarily been considered as a target in the treatment of inflammatory and autoimmune diseases; however, so far, no selective ITK inhibitors have entered clinical development." (PMID 33291717, 2020). "Our data show for the first time that ITK regulates CD4+ TREG and Th17 differentiation in primary human T cells, and highlights the potential for pharmacological targeting of specific Tec kinases in inflammatory and autoimmune disease." (PMID 31022269, 2019).
melanoma (10 papers, 2006 to 2025). A malignant, usually aggressive tumor composed of atypical, neoplastic melanocytes. "Previous studies examining ITK expression in solid tumors are limited to melanoma, in which aberrant expression was shown to be associated with poor outcome." (PMID 34283052, 2021). "ITK protein expression reportedly increases with nevus to metastatic melanoma progression and is associated with tumor development and progression in melanoma." (PMID 34283052, 2021). "As expected, B16-F10-OVA melanoma was only partially sensitive to anti-PD-1 therapy, moreover, the addition of ITK inhibitor treatment further improved tumor growth inhibition and animal survival." (PMID 37735204, 2023). "In vivo intermittent treatment of 3 ICB-resistant solid tumor (melanoma, mesothelioma or pancreatic cancer) with ITK inhibitor significantly improved ICB therapy." (PMID 37735204, 2023). "This antibody is the same as that used in a study in which the correlations between ITK expression and melanoma were evaluated by IHC using clinical samples." (PMID 34283052, 2021). "It was reported that ITK was aberrantly expressed in melanoma and promoted tumor development and progression." (PMID 31942187, 2020). "Furthermore, we demonstrated that differential expression of all investigated Ibrutinib target genes (i.e., BTK, EGFR, ERBB2, ITK, JAK3, and TEC) is associated with apoptotic mechanisms in clinical melanoma samples." (PMID 38790974, 2024). "Overall, the role of ITK in melanomas needs to be further elucidated." (PMID 32808093, 2020). "The 12 CpG loci identified by PAM analysis that provided the most accurate prediction of melanoma were RUNX3_P393_R, RUNX3_P247_F, RUNX3_E27_R, COL1A2_E299_F, MPO_P883_R, TNFSF8_E258_R, CD2_P68_F, EVI2A_P94_R, OSM_P188_F, ITK_P114_F, FRZB_P406_F, and ITK_E166_R." (PMID 21375697, 2011). "Finally, one study suggests that ITK might also play an important role in tumour proliferation in melanoma cells." (PMID 32808093, 2020). "While HFF-1 showed higher levels of EGFR (p = 0.001) and JAK-3 (p = 0.001) genes compared to MeWo, the melanoma cell line presented higher expression of ERBB2 (p = 0.001), and ITK (p = 0.04)." (PMID 38790974, 2024). "IHC using an anti-ITK antibody revealed aberrant expression of ITK protein in five patients with TSCC who had a significantly poor prognosis, a result similar to the previous melanoma study." (PMID 34283052, 2021). "Ibrutinib, an irreversible inhibitor of Bruton’s tyrosin kinase (BTK) and IL-2 inducible T-cell kinase (ITK) inhibited not only the generation of human MDSCs in vitro but also the recruitment of CD11b+/Gr1+ MDSCs in the tumor and spleen in murine breast cancer and melanoma models." (PMID 27886105, 2016).
breast carcinoma (8 papers, 2016 to 2023). "For ‘ITK’, the term identified in association with breast cancer is ‘EMT’, which is an alias of ‘ITK’ gene." (PMID 36699388, 2022). "Controversially, it was reported that ITK upregulation is associated negatively with the prognosis of breast cancer." (PMID 34282055, 2021). "Our present study is based on DC-mediated anticancer therapy using the potent ITK/BTK inhibitor ibrutinib in a murine model of breast cancer." (PMID 32025027, 2020). "ITK inhibitor ibrutinib inhibits luminal A breast cancer cells in vitro, represents safe treatment of solid tumors and is currently being tested in a phase II clinical trial in Her2+ breast cancer patients (trial number: NCT03379428)." (PMID 32947901, 2020). "Furthermore, the inhibition of ITK by Ibrutinib was reported to inhibit tumor development and metastasis in breast cancer." (PMID 36672350, 2023). "A previous study focusing on breast cancer stated that Ibrutinib, an ITK inhibitor, could suppress tumor development and metastasis by stimulating the development of mature DCs from myeloid-derived suppressor cells (MDSCs) and might be an effective therapeutic method to treat breast cancer." (PMID 34282055, 2021).
Immunodeficiency (8 papers, 2014 to 2025). Failure of the immune system to protect the body adequately from infection, due to the absence or insufficiency of some component process or substance. "The optimal treatment regimen still needs to be further explored, and the relationship between ITK gene mutation at this locus and immunodeficiency and EBV-SMT warrants further investigation." (PMID 37465420, 2023). "For example, biallelic mutations in the ITK gene locus result in a monogenetic disorder leading to T-cell dysfunction, and ITK deficiency is an immunodeficiency that causes Epstein‒Barr virus (EBV) associated diseases and results in an inability to control EBV infection." (PMID 37465420, 2023). "The dual ITK/TXK inhibitor RN694 exhibited efficacious effects in animal models of immune diseases such as colitis and psoriasis." (PMID 36821545, 2023). "Several immunodeficiency disorders associated with EBV lymphoproliferation have been described, including deficiency of ITK, XIAP, STK4, SH2D1A, and CD27." (PMID 27338827, 2016). "However to conclude human ITK physiology and primary ITK immunodeficiency from these inhibitors is quite ambiguous as this model reflects the acquired rather than the inherited innate ITK impairment." (PMID 25339095, 2014). "While NK cells might preferentially eliminate lytically EBV replicating cells, and immunodeficiencies that affect them could primary result in lymphoproliferations, NKT cells might be superior in restricting Hodgkin’s lymphoma and especially affected by ITK and CD70 deficiencies." (PMID 29225606, 2017).
primary immunodeficiency (8 papers, 2014 to 2023). "Prospective data collection on HSCT in ITK deficiency and other EBV prone primary immunodeficiencies, as CD27 or CD70 deficiency is highly warranted." (PMID 29867957, 2018). "Enrichment Kyoto Encyclopedia of Genes and Genomes (KEGG) analysis revealed DEGs engaged into three metabolic pathways: NF-kappa B signaling pathway (ZAP70, LCK, LTB), T cell receptor signaling pathway (ITK, ZAP70, LCK), and primary immunodeficiency (ZAP70, IL7R, LCK)." (PMID 30917529, 2019).
hemophagocytic lymphohistiocytosis (7 papers, 2018 to 2025). "Patients with interleukin-2-inducible T-cell kinase (ITK) deficiency is prone to lymphoproliferative diseases, including Hodgkin and non-Hodgkin lymphoma, EBV lymphoproliferative disease, and hemophagocytic lymphohistiocytosis." (PMID 37730603, 2023). "Individuals with mutations in the interleukin-2-inducible T-cell kinase (ITK) gene experience Hodgkin and non-Hodgkin lymphoma, EBV lymphoproliferative disease, hemophagocytic lymphohistiocytosis, and dysgammaglobulinemia." (PMID 29867957, 2018).
inflammatory bowel disease (7 papers, 2018 to 2026). A spectrum of small and large bowel inflammatory diseases of unknown etiology. "Not only TIM-3 but also ITK is involved in the development and maintenance of autoimmune diseases, like asthma and multiple sclerosis, or inflammatory bowel disease." (PMID 41483156, 2026). "This leads to the reverse conclusion that ITK might also play an important role in the development of inflammatory bowel disease." (PMID 32808093, 2020). "ITK harbors a variant (rs753847568, p.Val264Ile) associated with very early onset inflammatory bowel disease (VEO-IBD) according to the HGMD31." (PMID 37080976, 2023). "There is also some evidence that ITK might have a detrimental role in inflammatory bowel disease." (PMID 32808093, 2020).
allergic disease (5 papers, 2009 to 2023). An immune response that occurs following re-exposure to an innocuous antigen, and that requires the presence of existing antibodies against that antigen. "Elevated IL-4 levels observed in the context of the knockout of ITK have been suggested to be linked to weaker Th2 responses and Th1 cell expansion in a manner that may contribute to certain parasitic infections and allergic diseases." (PMID 37266435, 2023). "However, in order to select one we focused on ITK, because of its involvement in the polarization of Th2 cells and its location in a chromosomal susceptibility region for allergy." (PMID 19216740, 2009). "Clinical development of ITK inhibitors for treating autoimmune and allergic diseases is now also underway." (PMID 34283052, 2021). "Evidence, mainly from knockout mice, has suggested that ITK plays a particularly important function in Th2 cells and this has prompted significant efforts to discover ITK inhibitors for the treatment of allergic disease." (PMID 25250764, 2014). "The relevance of ITK was validated in a mouse model of allergy." (PMID 19216740, 2009). "The inhibition of ITK therefore may be a useful strategy to treat allergic diseases." (PMID 38201909, 2023). "Numerous previous studies have identified ITK as an important component of the TCR signalling complex and evidence from knockout mice have suggested it plays a particularly central role in Th2 function, so implicating it as a drug target for allergic diseases." (PMID 25250764, 2014).